SULF2 (sulfatase 2)
Diseases named in the same sentence as SULF2 in open-access papers (continued):
Sharing a sentence is not in itself a finding about the gene and the disease.
liver cancer (6 papers, 2011 to 2022). An epithelial or non-epithelial malignant neoplasm that arises from the liver. "Evidence from an investigation on liver cancer suggested that overexpressed SULF2 predicted a worse prognosis." (PMID 32049100, 2020). "A different study also reported increased expression of Sulf2 in liver cancer specimens compared to normal tissue counterparts." (PMID 25105093, 2014). "Future studies must examine the role of SULF2 in hepatitis, liver cirrhosis, and liver cancer." (PMID 33889573, 2021). "In addition, an over-representation of Sulf2 gene expression in skin cancer, colorectal carcinoma, testicular teratoma, and liver cancer compared to their normal tissue counterpart has been reported." (PMID 25105093, 2014). "Besides, we observed an over-representation of SULF2 gene expression in skin cancer, colorectal carcinoma, testicular teratoma and liver cancer compared to their normal tissue counterpart." (PMID 21599997, 2011). "In human liver cancer cells, OKN-007 was noted to have an anti-tumor effect by suppression of both the transforming growth factor β1 (TGFβ1)/SMAD and Hedgehog/GLII signaling pathway by inhibiting sulfatase 2 (SULF2) enzyme activity." (PMID 33168005, 2020).
multiple myeloma (6 papers, 2007 to 2016). "We demonstrated that SULF2 expression in primary multiple myeloma cells was associated with a poor prognosis in two independent large cohorts of patients." (PMID 21599997, 2011). "In addition to an association of heparanase with myeloma progression, Bret and colleagues discovered that Sulf2 expression in primary multiple myeloma cells were associated with a poor prognosis in two independent large cohorts of patients." (PMID 25105093, 2014).
colorectal carcinoma (5 papers, 2011 to 2025). A malignant epithelial neoplasm that arises from the colon or rectum and invades through the muscularis mucosa into the submucosa. "Further investigations revealed that Sulf2 was significantly overexpressed in high grade uveal melanoma compared to low grade and in patients presenting colorectal carcinoma compared to benign colon adenoma." (PMID 25105093, 2014). "We found that SULF2 was significantly over-expressed in high grade uveal melanoma compared to low grade and in patients presenting colorectal carcinoma compared to benign colon adenoma." (PMID 21599997, 2011).
glioma (5 papers, 2007 to 2024). A benign or malignant brain and spinal cord tumor that arises from glial cells (astrocytes, oligodendrocytes, ependymal cells). "SULF2 is the best tumor-dependent protein for glioma because the extracellular sulfatase SULF2 activates the RTK pathway." (PMID 39707577, 2024). "Although the function of SULF1 remains largely unknown, SULF2 was identified as a potential cancer-driving gene in unbiased screening studies of glioma and breast cancer." (PMID 26895473, 2016). "Interestingly, interaction of CSPG4 with PDGFRA has been shown to promote oligodendrocyte progenitor cells proliferation in response to PDGF43 and a HS modification enzyme, SULF2, is also able to mediate PDGFRA activity in glioma cells." (PMID 32019907, 2020).
head and neck squamous cell carcinoma (5 papers, 2015 to 2024). A squamous cell carcinoma that arises from any of the following anatomic sites: lip and oral cavity, nasal cavity, paranasal sinuses, pharynx, larynx, and salivary glands. "To test our hypothesis, we performed monoclonal antibody (mAb) affinity purification of the native Sulf-2 and its interacting partners from the conditioned media of head and neck squamous cell carcinoma (HNSCC) cell lines." (PMID 38825040, 2024). "In this study, we explored the effect of SULF2 expression on HSPG sulfation and its relationship to clinical outcomes of patients with head and neck squamous cell carcinoma (HNSCC)." (PMID 33585200, 2020).
astrocytoma (4 papers, 2012 to 2017). "In malignant astrocytoma, we recently determined that knockdown of SULF2 resulted in decreased activity of multiple RTK signaling pathways including PDGFR-alpha, IGF1R-beta and EPHA2, three pathways known to be involved in astrocytoma growth and invasion." (PMID 22643827, 2012). "Notably, there is a precedent for SULF modulation of EGFR signaling in that SULF2 knockdown in astrocytoma cells led to a reduction in EGFR activation, as well as that of several other receptor tyrosine kinases." (PMID 23950901, 2013). "Furthermore, ablation of SULF2, in a relevant murine model for astrocytoma, resulted in decreased activation of PDGFR-alpha, decreased tumor cell proliferation, and prolonged survival." (PMID 22643827, 2012).
bladder cancer (4 papers, 2022 to 2025). "In this study, the high expression of SULF2 by RNA sequencing of tissues from 90 bladder cancer patients was associated with poor prognosis in patients." (PMID 36612128, 2022). "Bladder cancer (BCa) exhibits SULF2-mediated IL-8 secretion through β-catenin, inducing M2 macrophage polarization via the JAK2/STAT3 signaling pathway." (PMID 40959082, 2025). "qPCR of mouse orthotopic bladder cancer tissue confirmed that the expression of IL8 decreased significantly after the knockdown of SULF2." (PMID 36612128, 2022). "However, the mechanism of SULF2 in bladder cancer (BCa) is unknown." (PMID 36612128, 2022).
gastric cancer (4 papers, 2013 to 2016). A primary or metastatic malignant neoplasm involving the stomach. "We examined gene expression of APTX, BRCA1, ERCC1, ISG15, Topo1 and methylation of SULF2 in formalin-fixed paraffin-embedded gastric cancer tissues from 175 patients and evaluated the association between gene expression levels or methylation status and in vitro sensitivity to irinotecan." (PMID 23517622, 2013). "In this study, we have analyzed the promoter CpG island methylation of SULF2, the gene encoding the SULF2 endosulfatase, and its association with in vitro sensitivity to cisplatin, docetaxel, gemcitabine, irinotecan, and pemetrexed in 100 human gastric cancer samples." (PMID 24124496, 2013). "Here, we focused our investigation on the prognostic and predictive impact of SULF2 methylation in gastric cancer." (PMID 24124496, 2013). "What makes the case even more interesting is that gastric cancer appearing with both SULF2 and WRN methylation is remarkably more sensitive with CPT-11." (PMID 24359226, 2013). "SULF2 methylation is a potential prognostic biomarker for gastric cancer patients treated with platinum-based chemotherapy." (PMID 24124496, 2013). "In another study, the expression of both SULF1 and SULF2 mRNA was determined by real-time RT-PCR for a large cohort of gastric cancer tissues, finding that SULFs were expressed at higher levels in gastric cancer as compared with normal tissues." (PMID 24124496, 2013). "This study focuses on the promoter CpG island methylation of SULF2 as a potential biomarker in gastric cancer." (PMID 24124496, 2013). "Multivariate analysis revealed that SULF2 methylation was an independent prognostic factor of overall survival in gastric cancer patients treated with platinum-based chemotherapy." (PMID 24124496, 2013). "Promoter CpG island methylation of SULF2 was analyzed in 100 gastric cancer samples." (PMID 24124496, 2013). "SULF2 methylation may be a novel prognostic biomarker for gastric cancer patients treated with platinum-based chemotherapy." (PMID 24124496, 2013). "Treatment of gastric cancer with DNMT inhibitors could result in demethylation of SULF2 and consequently increase the sensitivity to cisplatin." (PMID 24124496, 2013). "Additionally, 56 gastric cancer patients treated with a modified FOLFOX regimen(biweekly oxaliplatin plus 5-FU and folinic acid) were retrospectively analyzed to further evaluate the prognostic and predictive impact of SULF2 methylation in gastric cancer." (PMID 24124496, 2013). "SULF2 and WRN promoter methylation detection indicates potential predictive biomarkers to identify and target the most sensitive gastric cancer subpopulation for personalized CPT-11 therapy." (PMID 24359226, 2013). "Then, we retrospectively analyzed the SULF2 methylation in a cohort of 56 gastric cancer patients treated with a modified FOLFOX regimen and concluded that SULF2U serves as an independent prognostic biomarker in gastric cancer patients treated with a modified FOLFOX regimen." (PMID 24124496, 2013). "At present, no study has compared the correlation between SULF2, WRN promoter methylation and clinicopathological parameters of patients with gastric cancer and the sensitivity to irinotecan (CPT-11)." (PMID 24359226, 2013). "However, up to now, the correlation between SULF2, WRN promoter methylation and the chemosensitivity of irinotecan in gastric cancer has not been studied yet." (PMID 24359226, 2013).
liver fibrosis (4 papers, 2021 to 2023). "Our studies demonstrate that mice deficient in SULF2 have reduced liver fibrosis and that the in vitro knockdown of SULF2 significantly decreases the activity of TGF-β signaling in HSCs." (PMID 34771445, 2021). "Our data here demonstrates that mice deficient in sulfatase-2 have reduced liver fibrosis." (PMID 34771445, 2021). "Sulfatase-2 (Sulf2) also regulates hepatic fibrosis in mice induced by BDL or intraperitoneal injection of CCl4 or TAA through inhibiting TGF-β signaling." (PMID 38074679, 2023). "Sulf2 knockout (Sulf2-KO) mice showed significantly decreased collagen content and bands of bridging fibrosis compared with wild-type mice in all three models of hepatic fibrosis." (PMID 38074679, 2023). "Our data suggest that the modulation of SULF2 is a rational therapeutic strategy for the amelioration of liver fibrosis." (PMID 34771445, 2021). "In all three models of liver fibrosis, we observed significantly lower levels of hydroxyproline in the Sulf2-KO mice compared to the WT mice." (PMID 34771445, 2021). "Our aim in this study was to delineate the mechanistic role of sulfatase-2 in fibrotic liver disease using mouse and in vitro cell culture models of liver fibrosis." (PMID 34771445, 2021). "In this study, we focused on the mechanistic role of SULF2 in fibrotic liver disease in mouse models of liver fibrosis and under in vitro conditions using HSCs." (PMID 34771445, 2021). "Our findings highlight sulfatase-2 as a potential target for therapeutic intervention geared at reversing liver fibrosis." (PMID 34771445, 2021). "This mechanistic role of SULF2 is manifested in the amelioration of liver fibrosis in mice following the knockout of SULF2." (PMID 34771445, 2021). "Previous studies have demonstrated the correlation between SULF2 and the occurrence of liver fibrosis." (PMID 33889573, 2021). "To this end, we induced liver fibrosis in wild-type (WT) and SULF2 knockout (Sulf2-KO) mice (6–8 weeks-old) via bile duct ligation (BDL), intraperitoneal injection of carbon tetrachloride (CCl4) or thioacetamide (TAA)." (PMID 34771445, 2021). "We aimed to elucidate the mechanistic role of sulfatase-2 (SULF2) in liver fibrosis." (PMID 34771445, 2021). "The knockout of SULF2 significantly inhibited the occurrence of liver fibrosis." (PMID 33889573, 2021). "Our data highlight SULF2 as a suitable target for the amelioration of liver fibrosis." (PMID 34771445, 2021). "Our evidence here provides insight into a novel role for SULF2 in liver fibrosis." (PMID 34771445, 2021). "Pharmacologic inhibition of SULF2 may represent a novel therapeutic approach to improve liver fibrosis." (PMID 34771445, 2021). "Further studies are needed to elucidate the mechanism of SULF2 in inflammation and liver fibrosis." (PMID 33889573, 2021). "Indeed, a comparison of our top 25 DEGs with an earlier meta-analysis of NT-NASH of 206 NAFLD patients revealed greater overlap of wound healing or liver fibrosis and cirrhosis-related genes, including dystrobrevin alpha (DTNA) and sulfatase 2 (SULF2)." (PMID 37223041, 2023). "As inflammation, liver fibrosis, and HCC are correlated, SULF2 may play an important role in these processes." (PMID 33889573, 2021). "But the role of sulfatase 2 in liver fibrosis has not been closely examined." (PMID 34771445, 2021).
lung squamous cell carcinoma (4 papers, 2015 to 2022). "Also, 40 out of 40 (100%) early stage (I or II) squamous cell lung carcinoma samples had SULF2 staining." (PMID 26882224, 2016).
brain cancer (3 papers, 2015 to 2017). A primary or metastatic malignant neoplasm affecting the brain. "In brain cancer, SULF2 has been 7directly implicated in driving tumorigenesis in murine and human malignant gliomas." (PMID 26248280, 2015).
cervical cancer (3 papers, 2020 to 2021). A primary or metastatic malignant neoplasm involving the cervix. "Upregulation of SULF2 gene expression is associated with proliferation, invasion, and migration of cervical cancer cells by its regulation of the extracellular signal-related kinase (ERK)/AKT signaling pathway." (PMID 34900703, 2021). "SULF2 was upregulated in cervical cancer tissues, which was specifically associated with the clinical stage, histological differentiation, and lymphatic metastasis." (PMID 32049100, 2020). "However, there remains little information regarding the association between SULF2 and cervical cancer, and we postulated that SULF2 may exert its effect in the development of cervical cancer by regulating the ERK/AKT signaling pathway." (PMID 32049100, 2020). "SULF2 expression was detected in tumor tissues and tumor-adjacent normal tissues from cervical cancer patients." (PMID 32049100, 2020). "In further experiments, we treated HeLa cells with LY294002 (an AKT inhibitor) and U0126 (an ERK1/2 inhibitor), and the results showed that both LY294002 and U0126 abolished the promoting effect of SULF2 on the growth of cervical cancer cells." (PMID 32049100, 2020). "SULF2 is highly expressed in cervical cancer, and thus, downregulation of SULF2 can inhibit the ERK1/2 and AKT signaling pathways to suppress the proliferation, invasion, and migration of cervical cancer cells while facilitating apoptosis." (PMID 32049100, 2020). "We found that the cell proliferation of cervical cancer cells with SULF2 knockdown was significantly decreased compared with that of the control cells by MTT assays (P<0.05)." (PMID 32049100, 2020). "Lastly, the xenograft models in nude mice were constructed to validate the regulatory effect of SULF2 on cervical cancer growth in vivo." (PMID 32049100, 2020). "Collectively, in this study, we aimed to explore the mechanism of the SULF2-mediated ERK/AKT signaling pathway in cervical cancer to provide theoretical evidence and an experimental foundation for the development of clinical treatments for cervical cancer." (PMID 32049100, 2020). "The results in the SULF2 group were quite the opposite in which SULF2 facilitated the growth of cervical cancer cells, which was reversed by LY294002 or U0126." (PMID 32049100, 2020). "The objective of this study was to explore the role of the SULF2-mediated ERK/AKT signaling pathway in cervical cancer." (PMID 32049100, 2020). "Overall, the present work indicated that SULF2 was upregulated in cervical cancer, while downregulation of SULF2 suppressed the activity of the ERK1/2 and AKT signaling pathways." (PMID 32049100, 2020). "ERK inhibitor U1206 abolished the promoting effect of SULF2 on the growth of cervical cancer cells." (PMID 34037092, 2021). "Thus, it seemed reasonable for us to suppose an oncogene role for SULF2 in cervical cancer." (PMID 32049100, 2020). "Hence, SULF2 may be a novel target in the treatment of cervical cancer." (PMID 32049100, 2020). "Among 79 patients with cervical cancer, 46 of 79 (58.23%) cases revealed positive expression of SULF2 relative to their matched non-tumor adjacent tissues (15/79, 18.99%)." (PMID 32049100, 2020).
diabetes (3 papers, 2013 to 2021). "As expected, many genes merely changed in the sDM group, such as SULF2, GFAP, ABCG1, GCK, ISM1, and CORIN, have been associated with diabetes." (PMID 34880765, 2021). "Furthermore, treatment with SULF2 antisense oligonucleotides normalizes the defective clearance of TRLs that results from increased degradation of HSPGs by SULF-2 in animal models of diabetes." (PMID 24278138, 2013).
esophageal cancer (3 papers, 2016 to 2020). A primary or metastatic malignant neoplasm involving the esophagus. "In our initial investigations, we showed that higher levels of SULF2 protein as assessed by immunochemistry is associated with increased severity of disease and worse survival in patients with esophageal cancer." (PMID 26882224, 2016).
idiopathic pulmonary fibrosis (3 papers, 2014 to 2020). Idiopathic pulmonary fibrosis (IPF) is a nonneoplastic pulmonary disease that is characterized by the formation of scar tissue within the lungs in the absence of any known cause. "Recently, Sulf-2 overexpression has also been associated with idiopathic pulmonary fibrosis (IPF), most likely through the regulation of TGFβ1 signaling in Type 2 alveolar epithelial cells." (PMID 24459635, 2014). "For example, SULF2 is over expressed in idiopathic pulmonary fibrosis." (PMID 26151842, 2015). "Sulf2 mRNA is overexpressed in lung samples from human patients with idiopathic pulmonary fibrosis (IPF), and Sulf2 protein was specifically localized to the hyperplastic type II alveolar epithelial cells (AECs)." (PMID 26151842, 2015). "In line with this, Sulf-2 was overexpressed in idiopathic pulmonary fibrosis and would act as a regulator, in a negative feedback loop, of TGF-β1 signaling in type 2 alveolar epithelial cells." (PMID 32318065, 2020).
myocardial infarction (3 papers, 2021 to 2024). Gross necrosis of the myocardium, as a result of interruption of the blood supply to the area, as in coronary thrombosis. "Human myocardial infarctions in this study showed variable levels of SULF1/SULF2 increases in different patients or different parts of the same heart that could relate to the length of ischemia and distance from the ischemic injury." (PMID 34789772, 2021). "In vitro hypoxia of endothelial cells in this study clearly demonstrated the modulation of both Sulf1/Sulf2 and some growth factors that may help explain in vivo changes observed upon myocardial infarction or disease." (PMID 34789772, 2021). "Many myocardial samples generally showed increased SULF1/SULF2 expression in ischemic hearts following single or multiple myocardial infarctions irrespective of their age." (PMID 34789772, 2021).
osteoarthritis (3 papers, 2008 to 2024). A noninflammatory degenerative joint disease occurring chiefly in older persons, characterized by degeneration of the articular cartilage, hypertrophy of bone at the margins and changes in the synovial membrane. "Sulf-1 and Sulf-2 expressions in human articular cartilage from normal donors and patients with osteoarthritis (OA) and in normal and aged mouse joints were analyzed by real-time polymerase chain reaction, immunohistochemistry, and Western blotting." (PMID 18507859, 2008).